ADAM12 (ADAM metallopeptidase domain 12)
Diseases named in the same sentence as ADAM12 in open-access papers (continued):
Sharing a sentence is not in itself a finding about the gene and the disease.
clear cell renal cell carcinoma (2 papers, 2022 to 2023). "Screening genes highly correlated with ADAM12 in renal clear cell carcinoma resulted in 250 associated genes, of which 178 were upregulated and 72 were downregulated." (PMID 35094638, 2022). "Multivariate analysis revealed that ADAM12 mRNA expression was an independent risk factor for overall survival in patients with clear cell renal cell carcinoma." (PMID 35094638, 2022). "The mRNA expression of ADAM12 was analyzed using The Cancer Genome Atlas (TCGA) database and the Gene Expression Omnibus (GEO) database, and the protein expression level of ADAM12 in renal clear cell carcinoma cell lines was detected by Western blot analysis." (PMID 35094638, 2022). "We screened out one miRNA, namely hsa-mir-204-5p, which was negatively correlated with ADAM12 expression and lowly expressed in renal clear cell carcinoma." (PMID 35094638, 2022). "We found that the protein expression of ADAM12 was low in 293 T but high in 786-O and 769-P renal clear cell carcinoma cell lines." (PMID 35094638, 2022). "This study investigated the role of ADAM metallopeptidase domain 12 (ADAM12) in clear cell renal cell carcinoma (ccRCC)." (PMID 35094638, 2022). "This study aimed to investigate the prognostic value of ADAM12 in clear cell carcinoma of the kidney and comprehensively evaluate its potential value." (PMID 35094638, 2022). "The results of our analysis showed that ADAM12 expression was elevated in renal clear cell carcinoma, and ccRCC patients with high ADAM12 expression had significantly shorter survival than those with low ADAM12 expression." (PMID 35094638, 2022). "(A) Western blot assay of ADAM12 protein expression in three renal clear cell carcinoma cell lines 786-O, 769-P, and Caki-2, and one normal renal epithelial cell line 293 T, showing the elevated expression of ADAM12 in renal clear cell carcinoma cell lines." (PMID 35094638, 2022). "Moreover, the upstream lncRNA meeting the criteria of negative correlation with has-mir-204-5p expression was positively correlated with ADAM12 expression, which was elevated in renal clear cell carcinoma, and the expression was negatively correlated with patient survival time." (PMID 35094638, 2022).
colon adenocarcinoma (2 papers, 2021 to 2023). "Compared with the normal tissues, the expression and methylation level of ADAM12 in colon adenocarcinoma were significantly upregulated." (PMID 34604068, 2021). "A disintegrin and metalloprotease 12 (ADAM12) is a member of the multidomain protein family, but the mechanisms by which it affects prognosis and immune cell infiltration in patients with colon adenocarcinoma (COAD) remain unclear." (PMID 34604068, 2021).
diabetes (2 papers, 2017 to 2021). "Therefore, it is possible that diabetes and high levels of glucose increase local glucocorticoid levels which induce ADAM12 and increase EGF-EGFR interaction leading to EGFR phosphorylation and activity." (PMID 29221204, 2017).
fetal growth restriction (2 papers, 2011 to 2022). A fetus that does not grow beyond the 10th percentile of conventionally accepted weight for gestational age. "Analogous to ADAM12, the concentration of PSGs in maternal serum is lower in the case of fetal growth restriction and spontaneous abortion." (PMID 35806078, 2022).
head and neck squamous cell carcinoma (2 papers, 2020 to 2024). A squamous cell carcinoma that arises from any of the following anatomic sites: lip and oral cavity, nasal cavity, paranasal sinuses, pharynx, larynx, and salivary glands. "Supporting the importance of radiation in upregulating ADAM12, the authors demonstrated up-regulated ADAM12 expression in normal and tumor skin of an animal experimental model after UV irradiation, and in CAL-27 and HN4 head and neck squamous cell carcinoma cells after being irradiated with X-rays." (PMID 39596804, 2024).
Hypertension (2 papers, 2015). The presence of chronic increased pressure in the systemic arterial system. "It has been shown that MMP-7 and ADAM-12 are functionally connected in agonist-induced transcriptional events that may ultimately result in the development of hypertension and cardiovascular hypertrophy." (PMID 26571308, 2015).
Kashin-Beck disease (2 papers, 2016 to 2023). Disabling osteochondrodysplasia with osteosclerosis, cone-shaped metaphysis, and shortening of the diaphysis. "ADAM12 was identified as a susceptibility gene for the Kashin-Beck disease in humans, causing growth retardation." (PMID 38017417, 2023).
leiomyoma (2 papers, 2014 to 2023). A well-circumscribed benign smooth muscle neoplasm characterized by the presence of spindle cells with cigar-shaped nuclei, interlacing fascicles, and a whorled pattern. "Consistent with the microarray result, the expression level of ADAM12 determined by qPCR was higher in leiomyomas." (PMID 25268745, 2014). "The neighboring protein-coding gene ADAM12 was also downregulated in Intergenic 10 knockdown leiomyoma cells." (PMID 25268745, 2014). "Moreover, the expression level of ADAM12 was reduced in Intergenic 10 knockdown leiomyoma cells, suggesting that Intergenic 10 positively regulates the expression of its neighboring gene ADAM12." (PMID 25268745, 2014).
leukemia (2 papers, 2020 to 2024). A malignant (clonal) hematologic disorder, involving hematopoietic stem cells and characterized by the presence of primitive or atypical myeloid or lymphoid cells in the bone marrow and the blood. "The roles of ADAM12 in leukemia pathogenesis is still obscure and need further study since the expression of this gene was similarly down-regulated in both treatments." (PMID 32337016, 2020).
non-small cell lung carcinoma (2 papers, 2006 to 2023). A group of at least three distinct histological types of lung cancer, including non-small cell squamous cell carcinoma, adenocarcinoma, and large cell carcinoma. "Taken together, these results providing evidence for an overexpression of ADAM-12 and a lower expression of ADAMTS-1 in non-small-cell lung cancer suggest that these proteases play different functions in cancer progression." (PMID 16495931, 2006).
oral squamous cell carcinoma (2 papers, 2021 to 2023). "Also, γ-ray induces a dose-dependent upregulation of ADAM12 in oral squamous cell carcinoma cells." (PMID 37495855, 2023).
pancreatic adenocarcinoma (2 papers, 2012 to 2024). "To determine if Adam12 protein was overexpressed in the stroma of primary pancreatic adenocarcinomas, we performed immunohistochemistry on tissue microarrays." (PMID 22984426, 2012).
pregnancy disorder (2 papers, 2015 to 2021). A disorder that is related to pregnancy. "Therefore, ADAM12 has been shown to be upregulated in different cancer types, pregnancy disorders, and human OA cartilage." (PMID 25667922, 2015).
psoriasis (2 papers, 2013 to 2024). An autoimmune condition characterized by red, well-delineated plaques with silvery scales that are usually on the extensor surfaces and scalp. "ADAM12 is upregulated in the non-healing edge of chronic skin ulcers, whereas ADAM10, ADAM12, and ADAM17, MMP2, MMP9, MM12, and MMP7 are highly expressed in psoriasis, a common hyperproliferative and inflammatory skin condition." (PMID 38473275, 2024).
rectal adenocarcinoma (2 papers, 2021 to 2023). "Our observation in non-RT patients is supported by data from the Human Protein Atlas (proteinatlas.org), which shows that ADAM12 expression in colon and rectal adenocarcinomas of stages I-III does not correlate with patient survival." (PMID 37495855, 2023).
rectal cancer (2 papers, 2022 to 2023). A primary or metastatic malignant neoplasm that affects the rectum. "This shows the potential for serum ADAM12 to serve as a prognostic marker associated with a higher stage and recurrence in local rectal cancer." (PMID 35413826, 2022). "Thus, it is tempting to speculate that altered tumor vascularity may be implicated in the observed effect of ADAM12 on response to radiotherapy in rectal cancer." (PMID 37495855, 2023). "To recapitulate the upregulation of ADAM12 expression upon RT observed in rectal cancer patients, we tested the expression levels of ADAM12 in cancer cells following exposure to ionizing radiation in vitro." (PMID 37495855, 2023). "Analysis of ADAM12 expression in tissues from 158 rectal cancer patients showed that ADAM12 was upregulated at the protein level in primary tumors compared to normal mucosa." (PMID 37495855, 2023). "Taken together, this suggests that ADAM12 levels in the serum and urine of rectal cancer patients should be investigated in relation to response to RT." (PMID 37495855, 2023). "Here, we show that ADAM12 expression is upregulated in response to irradiation in both mouse and human cancer cells in vitro, as well as in tumor tissues from rectal cancer patients." (PMID 37495855, 2023). "In summary, we showed for the first time that ADAM12 could be a predictive marker for the stratification of rectal cancer patients before subjecting them to RT." (PMID 37495855, 2023). "Given that these findings could be translated to human rectal cancer patients, it could potentially explain the observed beneficial effects of RT in patients with weak ADAM12 expression." (PMID 37495855, 2023). "Interestingly, the expression of ADAM12 following radiotherapy correlates with the initial disease stage and predicts the response of rectal cancer patients to the treatment." (PMID 37495855, 2023). "We conclude that ADAM12 represents a promising prognostic factor for stratification of rectal cancer patients receiving radiotherapy and suggest that targeting ADAM12 in combination with radiotherapy could potentially improve the treatment response." (PMID 37495855, 2023). "To investigate the role of ADAM12 in the response of cancer patients to RT, we analyzed ADAM12 expression by IHC in formalin fixed and paraffin embedded samples from rectal cancer patients, who participated in the randomized Swedish rectal cancer trial of preoperative RT." (PMID 37495855, 2023). "The clinical value of ADAM12 was retrospectively assessed in the CAIRO2 trial in metastatic CRC with 235 patients (31% of total cohort), and an independent rectal cancer cohort (n = 20)." (PMID 35413826, 2022). "While this has not been reported for rectal cancer before, it aligns with previous observations that ADAM12 expression is increased in different types of cancers." (PMID 37495855, 2023). "ADAM12 also showed potential for predicting recurrence in an exploratory analysis of non-metastatic rectal cancers." (PMID 35413826, 2022).
rectal tumors (2 papers, 2022 to 2023). "To further study the prognostic value of serum ADAM12 in rectal tumors specifically, we performed an exploratory analysis in an independent cohort of 20 patients with early-stage and locally advanced rectal tumors." (PMID 35413826, 2022). "We currently have no full explanation for the association of ADAM12 high levels with poor prognosis specifically in rectal tumors; this can possibly be explained by a differential stromal recruitment and activation between tumors along the proximal-distal gastrointestinal axis." (PMID 35413826, 2022). "While limited by few samples exhibiting low ADAM12 staining, comparison of disease-free survival subdivided into stages I, II, and II indicated that strong ADAM12 expression in especially stage III rectal tumors is a good discriminator for patient survival post-surgery and RT." (PMID 37495855, 2023).
renal carcinoma (2 papers, 2022 to 2025). A carcinoma arising from the epithelium of the renal parenchyma or the renal pelvis. "The novel aspect of our work is that we not only found two genes (ADAM12 and CYP1B1) upregulated in CAAs of renal cancer but also, we observed that their expression correlates with BMI and is tightly linked with the overweight‐to‐obese degree of patients." (PMID 39806854, 2025). "Enhanced ADAM12 and CYP1B1 expression promotes tumorigenesis of renal cancer since their silencing reduces the tumor growth and cancer cell proliferation and migration." (PMID 39806854, 2025).
renal fibrosis (2 papers, 2015 to 2025). A final common manifestation of a wide variety of chronic kidney diseases characterized by glomerulosclerosis and tubulointerstitial fibrosis. "miR-29 has been also implicated in the regulation of Adam12 expression in response to transforming growth factor β (TGFβ) in experimental renal fibrosis in mice." (PMID 25886595, 2015).
scleroderma (2 papers, 2021 to 2025). Scleroderma is a rare autoimmune connective tissue disorder characterized by abnormal hardening of the skin and, sometimes, other organs. "Immunofluorescence staining results showed that the proportion of ADAM12+/NREP+ cells was higher in scleroderma tissue than in normal control tissue." (PMID 34140509, 2021). "In a skin tissue dataset, a fibroblast cluster expressing POSTN, ADAM12, and NREP was found to be higher in scleroderma than normal skin tissue samples." (PMID 40232153, 2025). "Mesenchymal fibroblast markers POSTN, ADAM12, COMP, and NREP were extensively expressed in scleroderma cluster 7 fibroblasts." (PMID 34140509, 2021).
systemic sclerosis (2 papers, 2017 to 2019). A chronic disorder, possibly autoimmune, marked by excessive production of collagen which results in hardening and thickening of body tissues. "In the context of fibrotic disease, the gp38 marker has been reported to be expressed in CD34−gp38+CD90+ reticular cells in the skin of the patients with systemic sclerosis and in mouse skin wounds as well as a subset of ADAM12+gp38+PDGFRα+ in skin and muscle acute injury stromal cells." (PMID 31417912, 2019).
trisomy 21 (2 papers, 2010 to 2012). A chromosomal disorder consisting of the presence of an extra chromosome 21. "However, there is debate as to the specificity of ADAM-12 with regard to differentiating EP from outcomes other than VIUP due to the fact that other conditions, such as trisomy 21 can also present with alteration of ADAM-12." (PMID 22927907, 2012).
uterine fibroids (2 papers, 2014 to 2015). "Based on our integrated analysis approach and qPCR validation, we found that CAR Intergenic 10 and its near protein coding gene ADAM12 were both up-regulated in uterine leiomyomas, which is consistent with previously reported in human fibroblast cells." (PMID 25268745, 2014).
abortion (1 paper, 2014). the ending of pregnancy by removing a fetus or embryo before it can survive outside the uterus. "In complete spontaneous abortion and ectopic pregnancy, ADAM12 maintained at low levels in early pregnancies, and there were significant differences compared to normal pregnancies." (PMID 24830297, 2014). "The MOM ADAM12 levels of the complete spontaneous abortion, ectopic pregnancy and hydatidiform mole groups are lower than the control group." (PMID 24830297, 2014). "In addition, ADAM12 levels have been shown to decrease in pregnancies that progress to complete spontaneous abortion." (PMID 24830297, 2014). "The data show that ADAM12 can discriminate the complete spontaneous abortion, the EP and the hydatidiform mole from normal pregnancies with good sensitivity and specificity, and suggest that the value of ADAM12 can be used as a potential biomarker for adverse pregnancy outcomes." (PMID 24830297, 2014).
adenoma (1 paper, 2024). A neoplasm arising from the epithelium. "Among them, two up-regulated (ADAM12, CEMIP) and one down-regulated (HHLA2) hub-genes have not been majorly highlighted for their contribution to adenoma-carcinoma transition, to the best of our knowledge." (PMID 38698020, 2024).
ameloblastoma (1 paper, 2020). The most common odontogenic tumor, arising from the epithelial component of the embryonic tooth and usually affecting the molar-ramus region of the mandible or maxilla. "As shown in ameloblastoma, transcription and post-transcription factors such as hypoxia-inducible factor 1α (HIF-1α), ADAM-12, and NOTCH1 are directly involved in an HB-EGF autocrine amplification loop and facilitate local tumor invasiveness." (PMID 31936715, 2020).
aneurysm (1 paper, 2025). Bulging or ballooning in an area of an artery secondary to arterial wall weakening. "Notably, a recent study found that Prdm16 ablation aggravates elastase-induced aneurysms in mice, through upregulation of ADAM12 and inflammatory signaling." (PMID 41107595, 2025).
aortic aneurysm (1 paper, 2023). A ruptured aneurysm located in the wall of the proximal portion of the descending aorta proceeding from the arch of the aorta. "More recently, ADAM12 was identified as a diagnostic indicator to classify ruptured intracranial aneurysm (IA) from unruptured IA along with several other biomarkers, suggesting a potential role in aortic aneurysm." (PMID 37079380, 2023). "ADAM12 is a member of the disintegrin and metalloproteinase family (ADAM), whose roles in aortic aneurysm are less explored." (PMID 37079380, 2023).
Autoimmunity (1 paper, 2013). The occurrence of an immune reaction against the organism's own cells or tissues. "In addition, ADAM12 could act through a novel mechanism to regulate IL-17-secreting Treg and Tm cell differentiation and functions, thus is a potential target to modulate Treg and Th17 cell actions in the context of inflammation and autoimmunity." (PMID 24363794, 2013).
brain tumours (1 paper, 2006). "Until recently, the ADAMs and ADAMTS genes were relatively understudied in brain tumours (and other cancers), however, recent reports have suggested roles for ADAMTS-4, TS-5 and ADAM-12 in GBM, where these proteases are overexpressed." (PMID 16570050, 2006).
breast invasive cancers (1 paper, 2017). "In addition, ADAM12 mRNA expression was strongly correlated with the EGFR activation score in 421 breast invasive cancers." (PMID 28148288, 2017).
breast invasive ductal carcinoma (1 paper, 2015). "As concerns the vascular cells, ADAM12 induced in endothelial cells of tumor vessels was suggested to be involved in tumor progression of breast invasive ductal carcinoma through processing vascular endothelial cadherin and Tie-224." (PMID 26242473, 2015).
Cirrhosis (1 paper, 2025). A chronic disorder of the liver in which liver tissue becomes scarred and is partially replaced by regenerative nodules and fibrotic tissue resulting in loss of liver function. "In our study, the methylation level of cg13674437/ADAM12 (a disintegrin and metalloproteinase) was lower, and cg06758847/PSD3 (Pleckstrin and Sec7 Domain Containing), and cg24595678/PSD3 were higher in cirrhosis patients who subsequently developed HCC than those who remained cancer-free." (PMID 39858049, 2025).
colon mucinous adenocarcinoma (1 paper, 2021). An invasive adenocarcinoma of the colon characterized by the presence of pools of extracellular mucin. "In addition, mucinous adenocarcinoma showed higher ADAM12 expression than adenocarcinoma." (PMID 34604068, 2021).
colorectal adenocarcinoma (1 paper, 2023). The most common type of colorectal carcinoma. "In the “colorectal adenocarcinoma TCGA Firehose Legacy” dataset, patients with a high expression of ADAM12 (z-score > 0.2) had a poorer overall survival ((OS); median OS = 63 months) compared to patients with a low ADAM12 expression (z-score < 0.2; median OS = undefined; p = 0.006; HR = 1.84)." (PMID 36675796, 2023).